SPARC (secreted protein acidic and cysteine rich)
Diseases named in the same sentence as SPARC in open-access papers (continued):
Sharing a sentence is not in itself a finding about the gene and the disease.
osteosarcoma (10 papers, 2006 to 2025). A usually aggressive malignant bone-forming mesenchymal neoplasm, predominantly affecting adolescents and young adults. "We further validated these candidates via the GEPIA database, narrowing down to COL1A1, PDGFRB, and SPARC as the most significantly associated with osteosarcoma progression." (PMID 41040657, 2025). "Another study, focused solely on osteosarcoma patients, evaluated SPARC by quantitative real-time PCR in initial diagnostic biopsies, primary resections, and metastatic disease." (PMID 27544129, 2016). "In particular, overexpression of SPARC, which was critical for the growth and maintenance of osteosarcoma, was found in 51 of 55 osteosarcoma tumor samples." (PMID 33195283, 2020). "Collectively, our results show for the first time that WIN is able to inhibit osteosarcoma cell migration in a SPARC-independent manner." (PMID 31652569, 2019). "Overall, these findings suggest that WIN markedly affects cell migration, dependently on miR-29b1 and independently of SPARC, and can thus be considered as a potential innovative therapeutic agent in the treatment of osteosarcoma." (PMID 31652569, 2019). "In a xenograft model of human osteosarcoma with high SPARC expression, nab-paclitaxel showed a tumor inhibition rate of 98.8%, which was greater than those of doxorubicin (46.1%) or paclitaxel (40.8%)." (PMID 26510912, 2015). "High SPARC expression was found in 51/55 (96.3%) osteosarcoma samples derived from 43 patients, and correlated with the worst event-free survival (p = 0.03) and relapse free survival (p = 0.07)." (PMID 17022822, 2006). "Our findings suggest that COL1A1, PDGFRB, and SPARC may be involved in mtRNA-driven tumorigenesis and could serve as promising therapeutic targets for osteosarcoma." (PMID 41040657, 2025). "Therefore, it is convincing that SPARC can serve as a biomarker or treatment target for osteosarcoma." (PMID 33195283, 2020). "Another important indicator, SPARC, is reported to be one of the candidate biomarkers of chemotherapy efficacy for pediatric sarcoma, including RMS, Ewing sarcoma, and osteosarcoma." (PMID 36918772, 2023). "The aim of the present study was to evaluate the effects of the cannabinoid WIN in osteosarcoma MG63 cell migration and the possible involvement of SPARC and miR-29b1 in this event." (PMID 31652569, 2019). "Since we previously demonstrated that, in osteosarcoma cells, the cytotoxic effect of WIN was accompanied by an increase in the level of SPARC, here, we aim to analyse a possible role of this factor in the anti-migratory effect of WIN in MG63 cells." (PMID 31652569, 2019). "THBS3, SPARC and SPP1 were identified by cDNA array as genes differentially expressed in osteosarcoma." (PMID 17022822, 2006). "Despite the fact that we have previously demonstrated a crucial role exerted by intracellular SPARC in WIN-induced apoptosis in osteosarcoma cells, in this paper, we demonstrate that SPARC is not involved in the anti-migratory effect of WIN." (PMID 31652569, 2019). "THBS3, SPARC and SPP1 were identified as genes differentially expressed in osteosarcoma." (PMID 17022822, 2006). "Furthermore, AMN1 and ZP3 may be protective factors in osteosarcoma (HR: 1.26e−36 and 1.13e−07, respectively), whereas LIMS1, SAMD4A, and SPARC appear to be harmful factors in this setting (HR: 699.2, 167, and 298.7, respectively)." (PMID 33195283, 2020). "Finally, we show the absence of SPARC in the extracellular vesicles released by osteosarcoma cells and no changes in SPARC level in miR-29b1 overexpressing cells." (PMID 31652569, 2019). "Moreover, as a confirmation that the anti-migratory effect of WIN was independent of SPARC, the knockdown of this factor by RNA interference did not influence the migratory ability of osteosarcoma cells either in the presence or absence of WIN." (PMID 31652569, 2019).
osteosarcoma (continued). "Similar to our results in soft tissue sarcoma, SPARC overexpression in osteosarcoma did not correlate with different time points of specimen collection (biopsy, surgical resection, and metastasis) or clinical and pathological variables such as age, gender, histology, or site of primary disease." (PMID 27544129, 2016).
acute myeloid leukemia (9 papers, 2010 to 2025). Acute myeloid leukemia (AML) is a group of neoplasms arising from precursor cells committed to the myeloid cell-line differentiation. "Recently, accumulating evidence suggested that SPARC overexpression is associated with poor outcome in acute myeloid leukemia (AML) patients and promotes the growth of aggressive leukemia cell in murine models." (PMID 31186631, 2019). "In contrast, lower levels of SPARC expression have been found in other types of cancers, such as ovarian, colorectal, pancreatic and acute myelogenous leukemia." (PMID 20525171, 2010). "In the present study, we investigated the role of SPARC in the proliferation and apoptosis of SKM-1 cells, an acute myeloid leukemia cell line transformed from an MDS cell line." (PMID 24535175, 2014). "In hematological diseases, SPARC has been evaluated on MDS 5q-syndrome and acute myeloid leukemia (AML) with MLL rearrangements." (PMID 23383963, 2013). "In this perspective, if the intracellular form of SPARC may protect CML cells from IM induced cell death, its secreted form could even be toxic for the CML cells as it has been demonstrated not only by our experiments but also for some subtypes of acute myeloid leukaemia." (PMID 23383963, 2013). "We also measured SPARC level in BCR/ABL positive cell lines (K652, LAMA84) and in HL60, a BCR/ABL negative acute myeloid leukemia cell line." (PMID 23383963, 2013). "However, the role of SPARC in other subtypes of myelodysplastic syndrome (MDS) is not fully understood, particularly in the del(5q) type with a complex karyotype, which has a high risk to transform into acute myeloid leukemia (AML)." (PMID 24535175, 2014).
disc degeneration (8 papers, 2011 to 2024). "Moreover, SPARC-deficient mice exhibit spontaneous disc degeneration and lower back pain, evidenced by an age-dependent increase in neuron markers like calcitonin gene-related peptide and Neuropeptide-Y within the discs and peripheral nerves." (PMID 38532900, 2024). "Additionally, the targeted deletion of the SPARC gene causes accelerated disc degeneration in old mice and behavioral phenotypes that are similar to chronic LBP in humans." (PMID 36768184, 2023). "In addition, aging mice showed decreased SPARC expression and increased methylation of the SPARC promoter, which are linked to chronic pain owing to disc degeneration." (PMID 36428977, 2022). "We then tested whether age-dependent disc degeneration in mice is associated with behavioral signs of axial and radicular pain and motor impairment, and whether it is impacted by loss of function of SPARC." (PMID 21867537, 2011). "It has been reported that SPARC expression decreased with increasing age and disc degeneration in human." (PMID 39507593, 2024). "The study suggests that the age-dependent methylation of the SPARC gene promoter induces SPARC silencing, thus contributing to disc degeneration and low back pain." (PMID 36768184, 2023). "In humans, decreased SPARC expression is observed in degenerating discs, and SPARC gene inactivation accelerates age-dependent disc degeneration, chronic pain, and physical disability." (PMID 36428977, 2022). "In this study, we used the SPARC-null mouse model of LBP due to disc degeneration (DD) to examine the effects of opioid-α2AR agonist combinations." (PMID 22577543, 2012). "Decreased expression of SPARC has been associated with aging and DD in human IVDs, and targeted deletion of the SPARC gene results in accelerated disc degeneration in the aging mouse." (PMID 22577543, 2012). "SPARC-null mice develop behavioural signs of axial pain by 4–6 months of age concurrent with disc degeneration." (PMID 22577543, 2012). "In humans, decreased expression of SPARC is observed in painful, degenerating discs and deletion of the SPARC gene triggers accelerated age-dependent disc degeneration and chronic pain in mice." (PMID 21867537, 2011). "In parallel, we show that human subjects with back pain exhibit signs of disc degeneration and increased methylation of the SPARC promoter." (PMID 21867537, 2011). "Targeted inactivation of the SPARC gene results in early onset of both disc degeneration and behavioral indices of LBP in mice." (PMID 21867537, 2011). "Our data shows that aging mice develop anatomical and behavioral signs of disc degeneration and back pain, decreased SPARC expression and increased methylation of the SPARC promoter." (PMID 21867537, 2011). "In mice, inactivation of the SPARC gene results in the development of accelerated age-dependent disc degeneration concurrent with age-dependent behavioral signs of chronic LBP." (PMID 21867537, 2011). "SPARC expression in human disc cells decreases with age and disc degeneration." (PMID 38532900, 2024). "Gruber showed that the deletion of the SPARC gene accelerated disc degeneration in the aging mouse." (PMID 32873329, 2020). "Thus, both normal aging and the deletion of the SPARC gene results in disc degeneration in mice, supporting a role for SPARC in maintaining disc integrity." (PMID 21867537, 2011). "The combination of the genetic evidence for the role of SPARC in chronic pain and the DNA methylation analysis provide strong support for the idea that DNA methylation occurs during aging and that it is involved in disc degeneration and chronic LBP." (PMID 21867537, 2011). "In humans, SPARC protein expression is decreased as a function of age and disc degeneration." (PMID 21867537, 2011). "The genetic evidence from mice and the clinical observation that SPARC is down-regulated in humans with disc degeneration suggests that long-term down-regulation of SPARC expression may play a critical role in chronic LBP." (PMID 21867537, 2011).
disc degeneration (continued). "Specifically, we present evidence from both mouse and human studies supporting the hypothesis that DNA methylation of the SPARC promoter is increased with age and intervertebral disc degeneration, resulting in the silencing of a gene that is protective against accelerated disc degeneration." (PMID 21867537, 2011). "SPARC promoter was significantly hypermethylated in patients with low back pain measured with ODI score (p < 0.01), in surgical patients (p < 0.05), and in lumbar disc degeneration based on MRI image scoring (p < 0.001) compared to IVD controls." (PMID 36768184, 2023).
dyslipidemia (8 papers, 2013 to 2024). "Together,these findings suggest that SPARC plays a fundamental role in dyslipidemia and in the development of atherosclerosis." (PMID 30875406, 2019). "Importantly, SPARC levels significantly correlated with inflammation and dyslipidemia, pointing to a potential involvement of SPARC in the pathophysiology of gestational diabetes mellitus." (PMID 33192583, 2020).
osteoporosis (8 papers, 2012 to 2025). A condition of reduced bone mass, with decreased cortical thickness and a decrease in the number and size of the trabeculae of cancellous bone (but normal chemical composition), resulting in increased fracture incidence. "COL6A2 and CPXM1, both associated with extracellular matrix composition and remodeling, were found to increase susceptibility to osteoporosis, whereas SPARC exhibited a protective effect, consistent with its known roles in bone matrix mineralization and osteoblast function." (PMID 41029778, 2025). "By integrating cis-eQTL, pQTL, and RNA-seq data, four candidate genes were identified with significant causal effects on osteoporosis risk, including COL6A2, CPXM1, MGP, and SPARC." (PMID 41029778, 2025). "Knockdown of SPARC attenuates fibrosis by reducing collagen expression, and SPARC plays important roles in the pathogenesis of osteoporosis because it regulates bone formation and remodeling by modulating the activities of osteoblasts and osteoclasts." (PMID 37569556, 2023). "SPARC has been reported to inhibit adipogenesis as evidenced by the phenotype of Sparc null mice exhibiting osteoporosis and fatty bone marrow." (PMID 30765860, 2019).
triple-negative breast carcinoma (8 papers, 2016 to 2024). An invasive breast carcinoma which is negative for expression of estrogen receptor (ER), progesterone receptor (PR), and human epidermal growth factor receptor 2 (HER2). "In triple negative breast cancer patients, high SPARC expression correlates with poor overall survival." (PMID 33534863, 2021). "Based on our results as well as reports that SPARC expression is related to therapy response in triple-negative breast cancer and in CRC, SPARC could be useful as a predictive marker." (PMID 31554208, 2019). "However, little is known regarding to the prognostic value of SPARC in triple-negative breast cancer (TNBC) patients." (PMID 27421134, 2016).
esophageal cancer (7 papers, 2006 to 2025). A primary or metastatic malignant neoplasm involving the esophagus. "These include SPP1 (osteopontin), SPARC, and POSTN (periostin), all of which have been implicated in esophageal cancer progression." (PMID 40872572, 2025). "In the epithelial cells of esophageal cancer, SPARC is extremely expressed." (PMID 37577749, 2023). "SPARC becomes a prominent target for esophageal cancer imaging." (PMID 37577749, 2023). "The expression of the SPARC gene is found to be increased in esophageal cancer." (PMID 37577749, 2023). "During the procedure of esophageal cancer, SPARC could be deployed as a potential medicinal target for endoscopic detection due to its extremely high expression in IHC." (PMID 37577749, 2023). "SPARC expression itself was shown to correlate with poor survival in esophageal cancer." (PMID 27391348, 2016). "SPARC has a strong correlation with MMP-2 expression, and this correlation could play a critical role in the growth of esophageal cancer." (PMID 37577749, 2023).
esophageal squamous cell carcinoma (7 papers, 2016 to 2024). Esophageal squamous cell carcinoma (ESCC) is a type of esophageal carcinoma (EC) that can affect any part of the esophagus, but is usually located in the upper or middle third. "Laminin-5γ2 chain and SPARC might participate in esophageal SCC progression, and their concurrent expression is associated with adverse prognosis." (PMID 37577749, 2023). "EN2 also promotes the invasion and metastasis of esophageal squamous cell carcinoma by upregulating SPARC expression." (PMID 36061185, 2022). "However, in another study investigating SPARC expression in patients with esophageal squamous cell carcinoma (SCC), the author evaluated the relationship between SPARC expression in the stroma and overall survival through two groups, stage-IIA/IIB and stage-III/IV esophageal SCC." (PMID 26731428, 2016). "And the result indicated that patients in stage-IIA/IIB, but not in stage-III/IV esophageal SCC with high SPARC expression, had a poor survival." (PMID 26731428, 2016).
fibrosis (7 papers, 2011 to 2025). the formation of excess fibrous connective tissue in an organ or tissue in a reparative or reactive process. "CCDC80, LAMA4, PDGFRB, PODN, and SPARC are potential mediators of intestinal fibrosis due to common expression among ileal and colonic strictures." (PMID 40398622, 2025). "In this study, a BLM-induced fibrosis mouse model was used to further confirm the regulating roles of SPARC in vivo." (PMID 39482755, 2024). "Other proteins such as TSP-1, OPN, proteoglycans lumican and agrin, and matricellular proteins SPARC and SMOC2 have a clear association with fibrosis in NAFLD patients and animal models." (PMID 33262757, 2020). "Finally, SPARC is a soluble protein and can be measured in serum, highlighting the need for further noninvasive and objective assessments of progressive fibrosis based on serum SPARC levels." (PMID 40719154, 2025). "The expression of SPARC, p38γ, 6-phosphofructo-2-kinase/fructose-2,6-biphosphatase 3 (PFKFB3), α-SMA, and Ki67 in patients with keloid and bleomycin (BLM)-induced fibrosis mice was assessed utilizing western blot, qRT-PCR, and immunohistochemical staining." (PMID 39482755, 2024). "Collectively, these data indicated that SPARC, p38γ, and PFKFB3 were upregulated in the skin of BLM-induced fibrosis model in C57BL/6 mice." (PMID 39482755, 2024). "SPARC, p38γ, and PFKFB3 were highly expressed in patients with keloid and BLM-induced fibrosis mice." (PMID 39482755, 2024). "In this study, we demonstrated that SPARC was upregulated in human keloid tissues and in skin tissues of BLM-induced fibrosis mice." (PMID 39482755, 2024). "In addition, the upregulation of SPARC, p38γ, and PFKFB3 were discovered in the skin of BLM-induced fibrosis mice model, and the inhibition of p38γ and PFKFB3 could relieve BLM-induced skin fibrosis." (PMID 39482755, 2024).
meningioma (7 papers, 2010 to 2022). A generally slow growing tumor attached to the dura mater. "In fact, SPARC has been proposed as a diagnostic marker of invasive meningiomas." (PMID 21152079, 2010). "Other molecules expression such as Vav3, SPARC, p-Akt, cyclin D1 and Ki-67 were found in meningiomas and correlate with meningioma invasiveness, aggressiveness and recurrence." (PMID 31123490, 2019). "SPARC is a matricellular protein that modulates cell adhesion and growth, along with cell-matrix interactions by binding to the extracellular matrix, and was suggested as a candidate biomarker for diagnosing invasive meningiomas." (PMID 31950035, 2019). "Increased SPARC expression is associated with the invasive phenotype in meningiomas, irrespective of tumour histological grade." (PMID 31123490, 2019). "SPARC can change the composition and structure of the matrix and promote angiogenesis; these effects are closely related to clinical stage and the prognosis of tumors such as meningiomas." (PMID 23516489, 2013).
nasopharyngeal carcinoma (7 papers, 2010 to 2017). A carcinoma arising from the nasopharyngeal epithelium. "In nasopharyngeal carcinoma patients, SPARC expression is also positively correlated with status of distant metastasis, world health organization histological classification, and poor prognosis." (PMID 28718842, 2017). "For instance, miR-29a/b was reported to enhance cell migration and invasion in nasopharyngeal carcinoma progression by regulating SPARC and COL3A1 gene expression." (PMID 26336827, 2015). "Decreased expression of SPARC, an important mediator of cell-matrix interaction, was previously observed in Nasopharyngeal carcinoma (NPC) and in the same system SOX-5 turned out to be upregulated." (PMID 20731828, 2010). "From these data we can assume that miR-29b has oncogenic activity by downregulating the tumour suppressor activity of PATZ1, in agreement with the ability of miR-29b to enhance cell migration and invasion in nasopharyngeal carcinoma progression by regulating SPARC and COL3A1 expression." (PMID 27125250, 2016).